CLDN5 (claudin 5)
Diseases named in the same sentence as CLDN5 in open-access papers (continued):
Sharing a sentence is not in itself a finding about the gene and the disease.
cognitive decline (12 papers, 2022 to 2026). "In a recent study, CLDN5 methylation has been shown to be associated with cognitive decline in the Religious Order Study-Rush Memory and Aging Project study." (PMID 37438770, 2023). "DNA methylation of Cldn5 was strongly linked to accelerated cognitive decline, even in individuals with low amyloid/tau burden, implying that vascular and barrier dysfunction may precede traditional AD pathology." (PMID 40940757, 2025). "Retinal claudin-5 deficiency has shown a significant association with cerebral amyloid angiopathy, while vascular zonula occludens-1 defects have been linked to cerebral pathology and cognitive decline." (PMID 41415892, 2025). "It is now likely that other channel-forming CLDN-5 mutants will be discovered as a causative factor for AHC or HM or novel loss-of-function CLDN-5 mutants may be discovered as a causative factor for mild cognitive decline or brain calcification in the basal ganglia." (PMID 36978081, 2023). "Therapies aimed at restoring BBB integrity, such as regulating tight junction protein Claudin-5 expression, may represent a novel strategy to prevent cognitive decline." (PMID 41602984, 2026). "Given that targets such as APOE, MMP9, and CLDN5 are linked to not just vascular pathology but also early-stage cognitive decline and neurovascular disturbance, the discovered ligands could be used to develop early intervention techniques." (PMID 41032496, 2025).
Cognitive impairment (11 papers, 2013 to 2024). Abnormal cognition is characterized by deficits in thinking, reasoning, or remembering. "The median plasma CLDN-5 level increased with cognitive impairment: 2.77, 2.91, and 3.08 ng/mL in the control, MCI, and AD groups, respectively." (PMID 38338697, 2024). "We and others have previously reported that high salt exacerbates cognitive impairment, and BBB leakage, with decreased gene expression of TJ associated proteins such as occludin, claudin-5 and zona occluding." (PMID 24339994, 2013). "This study showed that hypoxia led to cognitive deficits that might be associated with the BBB disruption in terms of the disarrangement of TJ and AJ proteins (tricellulin, VE-cadherin, and CLDN5)." (PMID 37605722, 2023). "Interestingly, intra-mPFC administration of oxytocin induce a significant increase of Claudin-5 protein levels accompanied with a reduction of EB staining that can reduce epilepsy development and improve cognitive impairments." (PMID 36997619, 2023). "Therefore, CLDN5 haploinsufficiency in 22q11DS may not be responsible for directly causing psychiatric disorders, but may be responsible for mild cognitive impairment like Cldn5+/− mice." (PMID 36978081, 2023). "Because reactive astrocytes and endothelial cells in the BBB in AD produce MMPs, prolonged activation of MMPs might lead to the degradation of CLDN-5 and, thus, lower plasma CLDN-5 levels in older compared with younger patients with cognitive deficits." (PMID 38338697, 2024). "Finally, administering WJ-MSCs after long-term hypoxia effectively reversed the cognitive deficits and prevented the BBB breakdown via the upregulation of VE-cadherin, claudin 5, and tricellulin genes (P<0.05)." (PMID 37605722, 2023).
endothelial dysfunction (11 papers, 2016 to 2025). In vascular diseases, endothelial dysfunction is a systemic pathological state of the endothelium (the inner lining of blood vessels) and can be broadly defined as an imbalance between vasodilating and vasoconstricting substances produced by (or acting on) the endothelium. "A recent study showed that Hedgehog signaling-induced endothelial dysfunction is associated with the reduction of CLDN5." (PMID 38186223, 2024). "Accordingly, this study also examined tight junction proteins that are closely associated with endothelial dysfunction, including ZO-1, Occludin, and Claudin-5, and found that tight junction protein expression was essentially reduced in the SHRs injected with D-gal for 12 weeks." (PMID 40080509, 2025). "It has also been found that tight junction proteins are proteins that regulate the permeability of the epithelial and endothelial tissue barriers, including ZO-1, Occludin, Claudin-5 and are closely related to endothelial dysfunction." (PMID 40080509, 2025). "In light of this, an upregulation of Cldn5 in db vitreous EVs suggests the potential endothelial origin of these EVs, implicating them in endothelial dysfunction and increased vascular permeability observed in DR." (PMID 39335566, 2024). "The expression levels of CLDN5, c1qRs, and C5 have been found to be altered in endothelial cells in COVID-19 patients, which has also been reported to play a role in endothelial dysfunction." (PMID 37239234, 2023). "We found unchanged expression of claudin-5 in X-ALD, whereas ZO-1 is expressed outside the vasculature, indicating endothelial dysfunction." (PMID 34082828, 2021). "We found unchanged expression of claudin-5, whereas ZO-1 expression is dislocated outside the endothelium, outside the UEA I positive RFs, pointing to endothelial dysfunction." (PMID 34082828, 2021). "Understanding the dysfunction and non-canonical roles of claudin-5 and occludin provides valuable perspectives for exploring therapeutic strategies targeting endothelial dysfunction in AVM pathology." (PMID 40429705, 2025). "We found that expression of the TJ marker claudin-5 is not altered, whereas that of ZO-1 is dislocated outside the vasculature, indicating endothelial dysfunction." (PMID 34082828, 2021).
lung carcinoma (11 papers, 2012 to 2025). "The hypoxia-induced increase in HIF-1α in lung cancer cells also causes a decrease in Claudin-5 expression, which increases the permeability of the blood–brain barrier, promoting lung cancer metastases to the brain." (PMID 40507913, 2025). "Results suggested that low doses of bevacizumab can increase CLDN5 expression to alleviate lung cancer metastasis, suggesting that CLDN5 is associated with anti-tumor immunotherapy." (PMID 37286335, 2023). "Some mechanisms have been proposed to explain the downregulation of CLDN5 expression frequently found associated with lung cancer brain metastasis." (PMID 33262947, 2020). "Similarly, Cldn5 overexpression in brain endothelial cells (hCMEC/D3) enhanced proliferation, migration, and adhesion, strengthening the barrier and limiting lung cancer metastasis to the brain." (PMID 40940757, 2025). "Interestingly, CLDN5 upregulation results in decreased the cell migration and invasion ability of lung cancer cells due to the decreased permeability of the cell membrane due to the enhancement of the CLDN5 tight junctions." (PMID 35563163, 2022). "Claudin-5 was highly expressed in lung cancer tissues and was a potential oncoprotein, which might be an ideal target for anti-cancer drug." (PMID 30874545, 2019). "Other lines of evidence indicate that claudin-5 expression is prominently decreased in human lung squamous cell carcinoma, whereas exogenous transfection of claudin-5 genes dramatically suppress the proliferation of lung cancer cells, possibly via inhibiting Akt phosphorylation." (PMID 28829370, 2017). "Beyond barrier function, Cldn5 may also act as a tumor suppressor in lung cancer." (PMID 40940757, 2025).
brain edema (10 papers, 2016 to 2026). Increased intracellular or extracellular fluid in brain tissue. "In hypoxic brain edema, Cav-1 forms membrane invaginations, facilitating claudin-5 endocytosis and subsequent autophagy, ultimately increasing BBB permeability and causing cerebral edema." (PMID 38922036, 2024). "Following siRNA mediated downregulation of claudin-5 in the cold-induced model of TBI, reduced claudin-5 expression enhances the movement of water from brain to blood, reducing cerebral oedema and accelerating neurological recovery." (PMID 30691500, 2019). "The quantification of VEGF, VEGFR2, ZO-1 and claudin-5 was used to illustrate the mechanism of 10 % HS ameliorating cerebral oedema." (PMID 27733124, 2016). "In recent years, some scholars have reported the close relationship between claudin-5 and brain edema." (PMID 27833554, 2016).
epilepsy (10 papers, 2019 to 2025). A brain disorder characterized by episodes of abnormally increased neuronal discharge resulting in transient episodes of sensory or motor neurological dysfunction, or psychic dysfunction. "In preclinical epilepsy models, microvascular Cldn5 stabilization reduced seizure susceptibility and neuroinflammation." (PMID 40940757, 2025). "Downregulation of claudin-5 is an early and prominent feature of MS and epilepsy, suggesting that early loss of claudin-5 and breakdown of paracellular BBB integrity is an important feature of the pathogenesis of these disorders." (PMID 30691500, 2019). "Furthermore, it is still unclear how claudin-5 expression alteration relates to epilepsy despite being linked to illnesses such as depression, schizophrenia, and traumatic brain damage." (PMID 41361096, 2025). "Importantly, almost half of patients with AHC develop epilepsy, but all patients with CLDN-5 missense mutations have epilepsy." (PMID 36978081, 2023). "Studies of surgically resected brain tissue from patients with treatment-resistant epilepsy have demonstrated reduced expression of claudin-5, with corresponding dynamic contrast-enhanced magnetic resonance imaging MCAO revealing significant BBB breakdown." (PMID 41361096, 2025). "The most recent literature clearly shows a compromised BBB with a decline in CLDN-5 expression increasing the risks of developing neuropsychiatric disorders, epilepsy, brain calcification and dementia." (PMID 36978081, 2023). "Here we report that claudin-5 protein levels are significantly diminished in surgically resected brain tissue from patients with treatment-resistant epilepsy." (PMID 35422069, 2022). "Here, we show for the first time, a direct correlation between human epilepsy and claudin-5 levels at the BBB." (PMID 35422069, 2022). "Based on our findings, the next logical step will be to assess the therapeutic efficacy of modulating claudin-5 in epilepsy models via small molecule regulation or gene therapy delivery of claudin-5 cDNA." (PMID 35422069, 2022). "In surgically resected brain tissue from individuals with refractory drug resistant epilepsy, claudin-5 staining was diffuse and discontinuous in blood vessels." (PMID 30691500, 2019). "Likewise, diminished Cldn5 levels are reported in epilepsy, traumatic brain injury (TBI), and multiple sclerosis (MS), where its loss correlates with increased barrier permeability and neuroinflammation." (PMID 40940757, 2025). "Added to this, the phenotype of mice with a 25% reduction in CLDN-5 is predicted to be much weaker than that of mice with 50% reduction of CLDN-5 that have previously shown significant memory impairment while also showing a lowered threshold of kainic acid-induced epilepsy." (PMID 38898501, 2024). "Finally, we identify that RepSox, a regulator of claudin-5 expression, can prevent seizure activity in experimental epilepsy." (PMID 35422069, 2022). "Overall, our findings suggest that epilepsy alters BBB integrity through modulation of the tight junction protein claudin-5 which facilitates a local inflammatory response and the passage of blood-derived proteins and immune cell infiltration into the brain parenchyma." (PMID 35422069, 2022). "Added to this, we observed granular pumilio-1 in endothelial cells in human brain tissues from patients with psychiatric disorders or epilepsy with increased/accumulated claudin-5 mRNA levels, suggesting translational claudin-5 suppression may occur in a brain-region specific manner." (PMID 38898501, 2024). "Additionally, targeted molecular or gene therapy-based approaches directly targeting claudin-5 could pave the way for a new generation of drugs to treat epilepsy and other neurological conditions where BBB breakdown is a hallmark pathology." (PMID 35422069, 2022).
epilepsy (continued). "The diffuse and discontinuous claudin-5 patterns of immunoreactivity we observed in resected hippocampus and cortex in the temporal lobe of patients with epilepsy suggests BBB dysfunction and claudin-5 dysregulation are key drivers of pathology." (PMID 35422069, 2022). "Furthermore, the inducible knockdown of claudin-5 in murine models results in severe neuroinflammation, increased mortality, and spontaneous recurrent seizures, highlighting the critical role of claudin-5 in maintaining BBB function and its potential as a therapeutic target in epilepsy." (PMID 41361096, 2025).
brain injury (8 papers, 2015 to 2025). Acute and chronic (see also brain INJURIES, CHRONIC) injuries to the brain, including the cerebral hemispheres, CEREBELLUM, and brain STEM. "Alterations in claudin-5 expression have been implicated in a number of neurological conditions including schizophrenia, depression, epilepsy and traumatic brain injury." (PMID 34867185, 2021). "To further unravel the transport across the BBB that is being altered, we analyzed the protein levels of endothelial claudin-5 and caveolin-1 (Cav-1), the latter has been associated with brain injury-related BBB breakdown." (PMID 30687711, 2018). "mRNA transcription and protein expression of TJ-associated proteins (claudin-5, occludin, and ZO-1) are significantly reduced following traumatic brain injury, and these changes are consistent with greater BBB permeability." (PMID 26290681, 2015). "Plasma neurofilament light (NFL) concentrations are correlated to claudin-5 concentrations post traumatic brain injury." (PMID 34604393, 2021). "Levels of circulating claudin-5 and occludin are increased after hypoxic/ischemic brain injuries and blood–brain barrier-impairment and have promise as early biomarkers for cerebral vascular dysfunction and as a tool for risk assessment of neonatal brain injuries." (PMID 33568200, 2021). "Our findings demonstrate that HGD intervention effectively restored the reduced expression of Claudin-5, Occludin, and ZO-1 induced by alcohol exposure, suggesting that HGD may enhance the structural integrity of the BBB in rats with alcohol-induced brain injury." (PMID 39229571, 2024).
COVID-19 (8 papers, 2021 to 2025). A disease caused by infection with severe acute respiratory syndrome coronavirus 2. "This approach identified autoantibodies targeting cardiolipin, platelet glycoprotein, and claudin 5 as the three most essential autoantibodies classifying severe COVID-19 patients <50 and ≥50 years old when compared with healthy controls at these ages." (PMID 37620330, 2023). "Intriguingly, our single-cell transcriptomics analysis showed the aberrant expression of CLDN5 in endothelial cells during COVID-19." (PMID 37239234, 2023). "The results suggest the importance of the autoantibodies targeting cardiolipin, platelet glycoprotein, and claudin 5 in the classification of COVID-19 patients." (PMID 37620330, 2023). "On the other hand, following the aging effect 1, autoantibodies against claudin 5 and enteric nerve showed a significantly reduced OR in severe COVID-19 patients <50 in relation to healthy controls." (PMID 37620330, 2023). "Single-cell transcriptomics analysis has revealed the aberrant expression of CLDN5 in endothelial cells during COVID-19, with the expression level of CLDN5 decreasing in endothelial cells compared to the control group." (PMID 37239234, 2023). "Since COVID-19 induces, in some patients, a thrombotic and microvascular injury syndrome, here, we have explored if placentas from women with COVID-19 exhibit an altered expression of vWf, claudin-5 and VE-cadherin in the decidua and chorionic villi." (PMID 33578631, 2021). "To test if COVID-19 induced damage to placental vessels, we analyzed the expression of VE-cadherin and claudin-5, the main molecular components of endothelial AJ and TJs, respectively." (PMID 33578631, 2021). "Since claudin-5 is the main claudin of endothelial cells, these results strongly suggest that TJs in the decidual endothelium and chorionic villi of women with COVID-19 become leaky as the severity of the disease augments." (PMID 33578631, 2021). "For this purpose, we have studied the expression of vWf, claudin-5, and vascular endothelial (VE) cadherin in the decidua and chorionic villi of placentas derived from women with mild and severe COVID-19." (PMID 33578631, 2021). "In contrast, lung tissue from patients with COVID-19 showed severely diminished and discontinuous claudin-5 and Col IV immunoreactivity." (PMID 34648357, 2021). "Next, we analyzed the expression of claudin-5 in the endothelium of the decidua and chorionic villi of control women and those with mild or severe COVID-19." (PMID 33578631, 2021). "The altered state of the endothelium in the decidua and chorionic villi of placentas from women with COVID-19 is further confirmed by a decreased expression of both claudin-5 and VE-cadherin in the placentas of women with severe COVID-19, suggesting enhanced vessel permeability." (PMID 33578631, 2021). "Cldn5 encodes a tight junction protein critical for BBB permeability, and its downregulation may reflect early BBB disruption, a finding consistent with neuropathological reports in COVID-19 patients." (PMID 41497643, 2025). "By immunofluorescence, we did not observe significant changes in the expression of claudin-5 in decidua and chorionic villi of women with mild COVID-19 in comparison to control." (PMID 33578631, 2021). "We found that while there is no significant change in expression of VE-cadherin and claudin-5 in the decidua and chorionic villi of placentas from women with mild COVID-19, the amount of both adhesion molecules decreases significantly in the tissues derived from women with severe COVID-19." (PMID 33578631, 2021).
experimental autoimmune encephalomyelitis (8 papers, 2015 to 2024). An autoimmune demyelinating disease of the central nervous system that is produced experimentally in animals by the injection of homogenized brain or spinal cord in Freund's adjuvant. "In experimental autoimmune encephalomyelitis (EAE), loss of claudin-5 is a primary event in affecting the BBB disruption due to the overexpression of VEGF-A from glial GFAP positive astrocytes." (PMID 35456999, 2022). "In line with this, in an experimental autoimmune encephalomyelitis model of MS, endothelial cells (ECs) secrete claudin-5 via extracellular vesicles (EVs), which are then taken up by leukocytes." (PMID 34082828, 2021). "In another study, the appearance of claudin-5 positive leucocytes around inflamed vessels in experimental autoimmune encephalomyelitis suggests that claudin-5 transfer from the endothelium to circulating leucocytes may facilitate immune cell transmigration." (PMID 35422069, 2022). "In experimental autoimmune encephalomyelitis, BBG-dependent P2 × 7R antagonism resulted in decreased BBB damage with normalized levels of PDGFβR and claudin-5 and pro-inflammatory cytokines, IL-1β, IL-6, and TNF-α." (PMID 39342243, 2024). "As an example, claudin 5-positive leukocytes emerge in the brain and blood in experimental autoimmune encephalomyelitis (EAE), which were found to occur from uptake of claudin-5 extracellular vesicles shed from brain endothelial cells." (PMID 32228633, 2020).